IGLC4 (immunoglobulin lambda constant 4 (pseudogene))
Synonyms: IGLC
Gene: Gene (Ensembl biotype IG_C_pseudogene) on chromosome 22 (22,910,828 to 22,911,075, forward strand). Ensembl gene ENSG00000254029.
Diseases named in the same sentence as IGLC4 in open-access papers:
IGLC4 is named in the same sentence as 1 disease in open-access papers, as found by Europe PMC text mining. Sharing a sentence is not in itself a finding about the gene and the disease. The quoted sentences say what the papers report.
tumor (1 paper, 2023). "Except for IGLC4, IGLC5, and IGLC7, 4 IGLC (IGLC1, IGLC2, IGLC3, and IGLC6) expressions were positively correlated with infiltration scores of 6 tumor-infiltrating immune cells (B cell, T cell CD4, T cell CD8, neutrophil, macrophage, and DC)." (PMID 37784026, 2023). "Except for IGLC4, IGLC5, and IGLC7, the expressions of 4 IGLCs were positively correlated with infiltration scores of some tumor-infiltrating immune cells respectively." (PMID 37784026, 2023).